TFPI (tissue factor pathway inhibitor)
Diseases named in the same sentence as TFPI in open-access papers (continued):
Sharing a sentence is not in itself a finding about the gene and the disease.
cancer (47 papers, 2008 to 2024). A tumor composed of atypical neoplastic, often pleomorphic cells that invade other tissues. "This mortality risk was confirmed by including sex, age, type of cancer, smoking habits, BMI, albumin, creatinine levels, traditional coagulation parameters (PT, aPTT, and fibrinogen), and total TFPI in regression models." (PMID 38282902, 2024). "The balance between TF and TFPI activity supported by a cancer cell reflects the real risk of thrombosis associated with cancer cells." (PMID 33668375, 2021). "TFPI can interact with various cellular signaling pathways implicated in cancer." (PMID 37759229, 2023). "Also, low levels of TFPI are associated with a bad prognosis in cancer cases." (PMID 36845546, 2023). "• A combination of a CD147 inhibitor and tissue factor pathway inhibitor (TFPI) can suppress the cancer-promoting actions of EVs." (PMID 38360687, 2024). "In a previous study, we showed that TFPI, which is released in response to the low-molecular-weight heparins (LMWHs) Tinzaparin, can suppress cancer cell progression induced by cancer-derived EVs." (PMID 38360687, 2024). "These gathered data together indicate a potential therapeutic value of TFPI regarding substantial inhibition of invasiveness and aggressiveness of certain different types of cancer and thus deceleration of cancer progression." (PMID 36900315, 2023). "Plasma concentrations of TFPI have been shown to be increased in patients suffering from GBM or different cancers (especially at the terminal stage of the disease) in comparison to healthy individuals." (PMID 33947134, 2021). "The mechanism involves the release of TFPI, which subsequently inhibits the tissue factor (TF) that can be expressed on cancer cell surface." (PMID 32679747, 2020). "The expression of TFPI has also been observed in some tumors and cancer cell lines, such as those from breast, pancreatic and colorectal cancer." (PMID 31212608, 2019). "Various studies have shown elevation of both TFPI and TF within cancer patients of different origin and subtypes, as well as in those with BrCa." (PMID 29475895, 2018). "TFPI acts in an inverse manner to TF and in the malignancy process, inhibits the cancer development." (PMID 29475895, 2018). "In conclusion, many biomarkers including factor VIII, D-dimers, VWF, free-TFPI and MV-TF activity are related to cancer process and elevated levels of D-dimers, MV-FT activity and CA 19-9 are risk factors for VTE in PDAC." (PMID 29899870, 2018). "While, TFPI has now been documented as having not only antitumour effects but also provoking apoptosis and suppressing proliferation and cancer invasion." (PMID 29475895, 2018). "We showed that fibrinogen, interleukin-6, factor VIII, D-dimers, VWF, free TFPI and extracellular DNA were higher in cancer patients than in both CP and IPMN patients." (PMID 29899870, 2018). "Increasing the FVIIa concentration to 100nM, (which saturated TF binding sites based on flow cytometric assessment) significantly increased the adhesion of cancer cells to immobilized TFPI in our study, particularly under shear conditions." (PMID 25849335, 2015). "Although we measured levels of TFPI instead of activity, this suggests that the behavior of plasma TFPI proceeds differently in different cancers." (PMID 25882602, 2015). "Factor VII was sufficient to mediate binding of high TF-expressing cancer cells to immobilized TFPI under static and low shear conditions, however the concentration of FVII was a limiting factor." (PMID 25849335, 2015). "Full-length tissue factor (TF) [GenBank: NM_001993] is the most extensively studied coagulation factor in cancer, and its activity is regulated by TF pathway inhibitor (TFPI)." (PMID 25882602, 2015). "We recently reported that both isoforms of TFPI induced apoptosis and inhibited proliferation of cancer cells." (PMID 23071754, 2012). "Circumstantial evidence suggests that tissue factor pathway inhibitor-1 (TFPI) plays a role in cancer development." (PMID 21849050, 2011).
cancer (continued). "TFPI was independently associated with risk of VTE and all-cause mortality in patients with cancer." (PMID 38891849, 2024). "Furthermore, we have demonstrated that TFPI released in response to an LMWH can effectively inhibit cancer cell migration induced by EVs derived from malignant effusions." (PMID 38360687, 2024). "Following these findings, it was suggested that restoration of TFPI might potentially be of antitumoral value due to the diminishment of cancer aggressiveness." (PMID 36900315, 2023). "It is thus reasonable to suspect that high plasma TFPI concentration may indicate a host compensatory mechanism resulting from a hypercoagulable state in cancer patients." (PMID 33947134, 2021). "We could not observe significant differences; only a trend of the increase was found in EVs TF/TFPI ratios of all cancer patients’ subgroups (before or after treatment) to their relative HC." (PMID 33108394, 2020). "Nevertheless, TF+EVs can be a surrogate parameter for the risk of developing cancer-associated VTE for individual patients and might indicate the use of low molecular weight heparins with the potency to release TFPI, such as tinzaparin." (PMID 31734835, 2020). "Even if it had been studied less, TFPI would have a role in cancer." (PMID 31212608, 2019). "In addition, TF and TFPI are also involved in maintaining pathological conditions, especially in cancer." (PMID 31212608, 2019). "Apart from the regular nature of cancer expressed by oversecretion of TF and suppression in realization of TFPI, our study revealed an interesting phenomenon in all patients from the study group; the levels of haemostatic parameters are aged- and menopausal-status dependent." (PMID 29475895, 2018). "In our study, we analysed BrCa patients according to the molecular nature of cancer and observed only higher concentrations of TFPI in luminal-A type as compared with other molecular types of BrCa, however only in the study group without comorbidities this observation was noted." (PMID 29475895, 2018). "Rather, the cancer cells would contact the immobilized TFPI and adhere immediately." (PMID 25849335, 2015). "TFPI may therefore represent a prognostic marker, but also an anti-cancer candidate with potential for being translated into the clinic." (PMID 25882602, 2015). "TFPI expression on endothelial cells is also increased in patients with cancer metastasis." (PMID 25849335, 2015). "Plasma levels of the coagulation inhibitors antithrombin and protein C have been shown to decrease, while tissue factor (TF) pathway inhibitor (TFPI) was found to increase during cancer progression, and several studies have shown that cancer patients acquire activated protein C (APC) resistance." (PMID 25407022, 2014). "Slightly heavier bands than previously reported for TFPI was observed, which may be due to cancer cell specific modifications." (PMID 23320987, 2013). "Emerging evidence indicate a new role of TFPI in cancer biology." (PMID 23071754, 2012). "Furthermore, genes involved in cellular processes such as adhesion, migration, invasion and colony formation were differentially expressed, indicating additional growth-related effects of either isoform of TFPI in the cancer cells." (PMID 23071754, 2012). "In addition, our findings show that increased expression of either isoform of TFPI affected the expression of genes involved in the immune response and development of cancer, linking these processes." (PMID 23071754, 2012). "Our results suggest an anti-metastatic effect of TFPI and may provide a novel therapeutic approach in cancer." (PMID 21849050, 2011). "Previous findings have, however, indicated an additional role of TFPI in cancer biology." (PMID 21849050, 2011). "To explore the possible role of TFPI in cancer cell growth, we investigated whether downregulation of TFPI would affect the cells ability to stimulate self-sustained growth." (PMID 21849050, 2011).
cancer (continued). "There is, however, a growing body of evidence of a new role of TFPI in cancer." (PMID 21849050, 2011). "Therefore, we speculate that TFPI could potentiate the suppressive effect of CD147 inhibitors on the protumoral functions of cancer-derived EVs." (PMID 38360687, 2024). "In contrast to TF, TFPI may have a beneficial effect on cancer cells and decreases the invasive potential of the disease, especially by inhibiting serine proteases such as matrix metalloproteases and plasmins involved in determining the aggressiveness of cancer." (PMID 31212608, 2019). "In addition, expression levels of cell cycle (CDK2, CDC2, CCND2) and inflammation markers linked to cancer (NOS2, TGFβ1, CHI3L1 and TFPI) were significantly increased in Caco-2WT/miR-373 compared with Caco-2WT/miR-c, but decreased in Caco-2D299G/α-miR-373 compared with Caco-2D299G/α-miR-c." (PMID 27271572, 2016). "However, more recent evidence indicates an additional role of TFPI in cancer." (PMID 23071754, 2012). "In the present study, TFPI was shown to exert an additional interfering effect when used in combination with a CD147 inhibitor, further suppressing autologous EV-induced cancer cell migration, MMP production, and invasion." (PMID 38360687, 2024). "We demonstrated that TFPI, a naturally occurring inhibitor of TF, enhances the suppressive impact of a CD147 inhibitor on cancer cell progression in vitro." (PMID 38360687, 2024). "Thus, the TFPI levels may vary according to cancer type and disease stage." (PMID 25407022, 2014). "In the cancer group, FVII Ag and total and free TFPI plasma levels were also determined." (PMID 38282902, 2024). "TFPI, TNC, and ELK3 are less studied in OV, but have been well researched in other cancer." (PMID 37759229, 2023). "TFPI works by blocking the activation of protease activated receptors 2 (PAR2), the activation of which plays an important role in the metastatic potential of this type of cancer." (PMID 34207591, 2021). "Furthermore, several cancer cell lines and tumors have been reported to express TFPIα, and enhanced levels of both TFPIα and TFPI-factor Xa (FXa) complexes have been detected in plasma of patients with solid tumors, supporting that TFPI may be involved in malignant disease mechanisms." (PMID 23320987, 2013). "Since increased APC resistance in cancer has been detected in several previous studies, adjustments were made for the hemostatic parameters that correlated to APC resistance; protein C (ρ = -0.18, P = 0.003), protein S (ρ = -0.33, P < 0.001), and free TFPI (ρ = -0.42, P < 0.001)." (PMID 25407022, 2014).
infection (18 papers, 2005 to 2025). The state of being infected such as from the introduction of a foreign agent such as serum, vaccine, antigenic substance or organism. "NE has been shown to degrade antithrombin and TFPI, thereby impairing natural anticoagulant mechanisms NE is also capable of causing tissue damage which reduces the ability of a host to fight infection." (PMID 31119471, 2019). "We previously demonstrated that higher levels of the tetrad heparanase, TF, TFPI, and TFPI-2 are present in hypercoagulable states as malignancy, recurrent abortions, pregnancy, and infection, mainly in the tissues’ microcirculation." (PMID 39766213, 2024). "Increasing evidence indicates that teleost TFPI is involved in antimicrobial immunity, and its expression has been considered to be induced by infection." (PMID 33632337, 2021). "Nebulization of rh-TFPI significantly attenuated the infection-induced increase in TATc and FDP levels and reduction of AT levels in lavage fluid compared to rats treated with vehicle." (PMID 25992779, 2015). "Notably, the levels of Tissue Factor Pathway Inhibitor 1 (TFPI1) at 6 h postinfection were depleted rapidly, strongly suggesting a prothrombotic priming of the liver vasculature very early during infection." (PMID 35913192, 2022). "The authors estimated that the inactivation rate of the naturally occurring, glycosylated TFPI by Pla is significantly higher than plasminogen activation by Pla and hence proposed that TFPI inactivation and fibrin formation protect Y. pestis during early stages of the infection." (PMID 23898467, 2013). "On the other hand, TFPI is sensitive to inactivation by several host proteases (such as MMPs, elastase, thrombin, FXa, and plasmin), which are released from leukocytes or upregulated in coagulation, and TFPI inactivation is thus expected to increase during infection." (PMID 23898467, 2013). "Expression of TFPI-1 and TFPI-2 are increased under stimulation with inflammatory mediators, endotoxin, or molecules involved in infection and inflammation." (PMID 33632337, 2021). "In a broader perspective, a picture thus emerges; suggesting that C-terminal fragments from both TFPI-1 and TFPI-2 may be released during inflammation and infection, serving as modulators of both antimicrobial activity and coagulation." (PMID 27349742, 2016). "On a systemic level (plasma) 12 h post-infection IL-6, IL-10, and MCP-1 was higher in TFPI-2−/− mice and no significant changes were observed in INF-γ, TNFα, and IL-12p70, whereas in BALF fluid, IL-10, and MCP-1 was higher in TFPI-2−/− mice." (PMID 30254643, 2018).
cardiovascular disease (8 papers, 2011 to 2025). "Several investigations focusing on the association between polymorphisms of the TFPI and cardiovascular diseases have been done to make clear the crucial role of TFPI." (PMID 28716011, 2017). "Effect of cardiovascular disease risk factors on the concentration of TF and TFPI (univariate linear regression)." (PMID 28749986, 2017). "Although TFPI, a protein involved in regulating coagulation, has been hypothesized to be associated with cardiovascular disease, its predictive potential for adverse cardiovascular events is unclear." (PMID 40710778, 2025). "Future studies of TFPI in cardiovascular diseases focusing on the role of TFPI activity and different TFPI isoforms in the development of atherogenesis could provide further insights." (PMID 36253349, 2022). "In a large, multiethnic cohort free of cardiovascular disease and with a spectrum of kidney function ranging from normal to moderate CKD, even small decrements in eGFR were associated with significantly higher levels of sTM, sTF, D-Dimer, vWF, factor VIII, PAP and TFPI." (PMID 21269477, 2011).
inflammation (2 papers, 2017 to 2025). Aberrant reaction of the microcirculation characterized by movement of fluid and leukocytes from the blood into extravascular tissues. "These include the downregulation of natural anticoagulants present on the EC surface (TFPI, TM, and EPCR) mediated by TNF-α and IL-1β, as demonstrated in both acute and chronic inflammation, and variation of protein S and upregulation of endothelial adhesive molecule expression." (PMID 39877523, 2025).
renal disease (2 papers, 2019 to 2022). "Despite all of these reports, urine d-dimer was clearly outperformed by other urinary markers in this study, notably urine plasmin and TFPI, in discriminating renal disease in SLE." (PMID 31319876, 2019). "Next to plasmin, urine TFPI emerged as the only other independent predictor of eGFR and renal disease status in our study." (PMID 31319876, 2019).
immune disorders (1 paper, 2021). "Our results showed a panel of three downregulated miRNAs (hsa-miR-4516, hsa-miR-494-3p and hsa-miR-542-3p) involved in the regulation of genes associated with viral latency (SUPT16H, TFPI), HIV reactivation (PIM1) and persistent metabolic and immune disorders (ZADH2, CCL16)." (PMID 34829855, 2021).
TFPI also shares sentences with these, for which no sentence is quoted: acute myocardial infarction (3 papers); Disseminated intravascular coagulation (3); glioblastoma (3); leukemia (3); cerebrovascular disease (2); complication (2); lung injury (2); lymphoma (2); osteosarcoma (2); abscess (1); acute gastritis (1); adenocarcinoma (1); adenovirus infection (1); atrial fibrillation (1); bleeding (1); brain cancer (1); cardiac arrest (1); cardioembolic stroke (1); Cognitive impairment (1); colon adenocarcinoma (1); colorectal cancer (1); depression (1); digestive system disorder (1); Disorder of lipid metabolism (1); disorders of arteries (1); factor V deficiency (1); fascioliasis (1); fetal growth restriction (1); fibroid (1); fibrosarcoma (1).
A further 29 diseases each share a sentence with TFPI in 1 paper.